IL6 (interleukin 6)
Diseases named in the same sentence as IL6 in open-access papers (continued):
Sharing a sentence is not in itself a finding about the gene and the disease.
colorectal tumor (continued). "However, we were unable to reliably identify regions of IL-6 expression in the colorectal tumours due to deep background staining, which precluded accurate scoring of IL-6-positive cells in the tumour tissue." (PMID 15700032, 2005). "In addition, immunohistochemistry for vascular endothelial growth factor-A and interleukin-6 was performed on colorectal tumours of such patients." (PMID 12454774, 2002). "In the AOM/DSS-induced orthotopic CRC model, KGM-PTX/CSM significantly inhibited colorectal tumor growth, improved survival rates, and suppressed inflammatory cytokine expression (TNF-α, IL-1β, IL-6, and IL-10) in serum and colorectal tissues." (PMID 40528838, 2025). "Elevated cytokines such as IL-6 and TNF-α promote colorectal tumor initiation and progression via inflammatory and proliferative mechanisms." (PMID 40399803, 2025). "Aggravation of colorectal tumors; induction of inflammatory cytokines and pathways (TNF-α, IL-1β, IL-6, IL-10)." (PMID 35893902, 2022). "Therefore, suppression of IL-6 may be a potential therapeutic strategy for colorectal tumors." (PMID 29707119, 2018). "In our study, we found that the level of IL-6 in TIF from 8-, 13-, 18- and 22-week APCMin/+ mice was correlated with the occurrence and development of colorectal tumors." (PMID 29707119, 2018). "Encouragingly, crocin also markedly reduced the numbers and size of colorectal tumors in CRC mice, and this was shown to occur via the anti-inflammatory activity of crocin, as evidenced by its influencing of ILs, especially those of IL-6, in the colon tissues and sera." (PMID 33841156, 2021). "Thus tRXRα expression in myeloid cells can induce IL-6 expression and STAT3 activation in colorectal tumor." (PMID 30931933, 2019). "It seems that IL-6 as a predictive factor for benign disease is affected by medication and might not be as accurate as for patients with colorectal tumours." (PMID 38098074, 2023).
coronary atherosclerosis (41 papers, 2009 to 2026). Atherosclerosis of the coronary vasculature. "In agreement with this, circulating levels of inflammatory markers such as CRP, erythrocyte sedimentation rate, and IL‐6 in RA patients are associated with a risk of cardiovascular events and with radiologic measures of coronary atherosclerosis." (PMID 35583917, 2022). "Several studies have suggested different SNPs in the IL-6/IL-6R were associated with several inflammatory cytokines and in relation to the susceptibility to coronary atherosclerosis." (PMID 36060677, 2022). "In another study called SIRCA (Study of Inherited Risk of Coronary Atherosclerosis), circulating leptin was associated with inflammatory factors (IL-6, CRP, and TNF-α) and also represented an independent marker for coronary artery calcifications." (PMID 24616817, 2014). "Coronary atherosclerosis is a chronic inflammatory disease process which has been associated with IL6." (PMID 23953602, 2013). "For SSc this is a new observation but IL-6 has been identified as a risk factor for subclinical coronary atherosclerosis in RA, and it has also been linked to poor prognosis in patients with IHD from the general population." (PMID 23945149, 2013). "Tumor necrosis factor-alpha (TNF-α) and interleukin-6 (IL-6) are significantly associated with coronary atherosclerosis." (PMID 19551157, 2009). "Furthermore, in the REPREIVE trial, IL-6 was independently associated with coronary atherosclerosis in PWH." (PMID 41488698, 2026). "Moreover, TNF-α and IL-6 are important pro-inflammatory factors that promote the accumulation of immune complexes in endothelial cells, which increase the risk of thrombosis and participate in the vascular inflammatory response and coronary atherosclerosis." (PMID 40584629, 2025). "Nevertheless, data of other inflammatory biomarkers, for example IL-6, would have added information about the role of systemic inflammation in coronary atherosclerosis." (PMID 37500663, 2023). "One recent study characterized coronary atherosclerosis as the concomitance of macrophage polarization with a greater expression of interleukin-6, tumor necrosis factor-alpha and monocyte chemotactic protein-1." (PMID 37380905, 2023). "A large number of studies have shown that IL-6 plays a key role in the progression of coronary atherosclerosis." (PMID 34660716, 2021). "In fact, activation of NF-κB is implicated in pathological inflammation, promoting the transcription of pro-inflammatory cytokines, such as TNF-α and IL-6, which are involved in the progression of coronary atherosclerosis." (PMID 32640692, 2020). "However, it should be noted that the increase in Il-6 represents a link between inflammation process and coronary atherosclerosis as has been attempted by several clinical trials." (PMID 39456434, 2024). "The results showed that RA was positively correlated with coronary atherosclerosis (OR: 1.0015, 95%CI 1.0004–1.0026, P < 0.05), and IL-6 was negatively correlated with coronary atherosclerosis (OR: 0.9911, 95%CI 0.9855–0.9967, P < 0.05), but the number of SNPS included was less." (PMID 37187788, 2023). "The proportion of sub-clinical coronary atherosclerosis was similar between both IL-6 groups." (PMID 36028849, 2022). "In the present study, we report that monocyte Sirt1 gene expression is decreased in patients suffering from coronary atherosclerosis; in line with this, expression of Sirt1-negatively regulated downstream target interleukin-6 (IL-6) was increased in the same patient groups." (PMID 23382833, 2013). "Future studies to probe mechanisms will include blockade of VCAM-1, TNFα or IL-6 or depletion of neutrophils to examine the extent to which increased VCAM1, TNFα, IL-6 and neutrophilia with advanced age drives the increased burden of coronary artery atherosclerosis." (PMID 40403091, 2025).
coronary atherosclerosis (continued). "We may speculate that TNFα and IL-6 may play a primary role in the promotion of coronary atherosclerosis, although the lack of a time-course observation in our experimental setting did not allow us to support this assumption with data." (PMID 39456434, 2024). "Plasma resistin levels were found to be correlated with markers of inflammation, such as IL-6 and TNF-α, and thus could predict coronary atherosclerosis in humans independent of CRP." (PMID 34209146, 2021).
Hypoglycemia (41 papers, 2012 to 2026). A decreased concentration of glucose in the blood. "High blood glucose, replacing hypoglycemia, caused a further increase in the concentrations of IL-6." (PMID 37893217, 2023). "Similar results were observed in this study; our data revealed that endotoxins cause significant systemic inflammation (upregulation of TNF-α, IL-6, and leptin in plasma) and metabolic alterations (body weight loss and severe hypoglycemia) in obese mice." (PMID 35056093, 2021). "High blood glucose, replacing hypoglycemia, caused a further increase in the concentrations of sICAM-1 and IL-6." (PMID 34360550, 2021). "In addition, elevated levels of inflammatory factors such as TNF-α and IL-6 have been observed in hypoglycemia, causing an acute inflammatory state in the organism." (PMID 34899278, 2021). "In addition, greater glycemic variability and hypoglycemia burden in T1D have been linked to systemic inflammatory responses that may upregulate IL-6." (PMID 41010714, 2025). "In a rat model of lipopolysaccharide (LPS)-induced AKI, both HIF-1α and aquaporin-1 (AQP1) were significantly upregulated within 12 h, concomitant with hypoglycemia, enhanced glycolysis, and a pro-inflammatory shift (elevated IL-6/TNF-α and reduced IL-10)." (PMID 41602837, 2026). "In individuals with T1D, an episode of two-hour hypoglycemia was followed by an increase in the levels of IL-6." (PMID 37893217, 2023). "A significant increase in interleukin-6 was seen in both control and in T2D subjects at 4-h after induced hypoglycemia." (PMID 34426634, 2021). "The stimuli for SIADH include nausea/vomiting, hypoglycemia, hypotension, interleukin-6 (IL-6) release, and hyperthermia, all of which can occur with prolonged exercise." (PMID 31181616, 2019). "Nausea/vomiting, heat, stress, inflammatory markers (i.e., interleukin-6), hypoglycemia and hypovolemia remain at the forefront of potential exercise-induced non-osmotic stimuli." (PMID 30678725, 2019). "The factors which have a decisive influence on the stimulation of the synthesis of this cytokine are hypoxia, hypoglycemia, and interleukin-1 (IL-1) and interleukin-6 (IL-6)." (PMID 31360727, 2019). "We demonstrated that the expression of TNF-α, IL-1β, and IL-6 was increased following acute severe hypoglycemia." (PMID 29793504, 2018). "Changes in glucose homeostasis during infection are context-dependent and poorly understood with cytokines such as IL-6 reportedly promoting hypoglycemia during acute LPS-induced inflammation." (PMID 27118537, 2016). "To assess the role of IL-6 with the second highest serum levels of anti-CD3 treated mice in anti-CD3-induced hypoglycemia, we tested how anti-IL-6 neutralizing antibodies affected blood glucose levels." (PMID 24741590, 2014). "After 2 h of hypoglycemia, flow mediated vasodilation significantly decreased, while sICAM-1, 8-iso-PGF2a, nitrotyrosine and IL-6 significantly increased." (PMID 23806096, 2013). "Prophylactic administration of bezlotoxumab prevented infection-mediated hypoglycemia, uremia, and a spike in IL-6 when compared to infected mice that received PBS (p = .0159), and a moderate, yet not significant reduction in creatinine levels compared to infected mice that received PBS." (PMID 36045589, 2022). "Bezlotoxumab treatment of infected mice was able to prevent infection-mediated hypoglycemia and an increase in serum IL-6 when compared to infected PBS-treated mice (p = .0159), with treated, infected mice showing similar glucose and IL-6 levels to uninfected mice." (PMID 36045589, 2022). "The pro-inflammatory cytokine, IL-6, increased at 4-h post-hypoglycemia in controls and T2D (p < 0.05 and p < 0.003, baseline vs 4-h, respectively) whilst the anti-inflammatory cytokine, IL-10, decreased 2-h post-hypoglycemia in T2D (p = 0.0001, baseline vs 2-h)." (PMID 34426634, 2021). "Effect of hydroxychloroquine on IL-6 and cytokine may responsible for less hypoglycemia as seen in several trails including the current one." (PMID 32594451, 2021).
Hypoglycemia (continued). "This suggested that suppression of PPAR-γ expression may be involved in the high levels of TNF-α, IL-1β, and IL-6 induced by hypoglycemia." (PMID 29793504, 2018). "Among these three concentrations, 25% PF127 gel formulation was found to be the best one that prolonged the in vitro and in vivo release, showed greater efficacy to induce hypoglycemia and inhibited IL-1β-stimulated production of IL-6 in wistar rats when compared with that of IL-1Ra solution." (PMID 23409091, 2013). "The previously reported association between cortisol responses and the IL-6 response to hypoglycemia could not be confirmed in this study." (PMID 37400734, 2023). "Molecules such as CXCL10 and IL-6 have been reported to be involved in abnormal glucose metabolism by inhibition of hepatic gluconeogenesis decreasing the concentration of glycemia in the blood, which may explain our result in patients with hypoglycemia." (PMID 36178979, 2022). "In accord with that interaction, here IL-6 correlated with HSPAIA in controls alone, suggesting that it was associated with the HSP response and is perhaps dysregulated in T2D, though it cannot be excluded that the elevation in IL-6 was an independent effect in response to the hypoglycemia." (PMID 34426634, 2021). "Moreover, the muscle defects are transmitted systemically through muscle release of fibroblast growth factor 21 (FGF21), together with inflammatory cytokines such as interleukin 6 (IL6) inducing hypoglycemia, lipolysis, liver steatosis, inflammation, a pro-senescent phenotype, and premature death." (PMID 33374852, 2020). "Furthermore, plasma glucose levels correlated negatively with brain levels of mRNAs encoding TNF-α, IL-1β, IL-6, CCL2 and iNOS, suggesting that hypoglycemia and the expression of these pro-inflammatory markers might be linked." (PMID 30375380, 2018). "Hypoglycemia was related to low IL-4, CXCL10, IL-6, and IFN-γ concentrations, regarding patients with normal glycemia concentrations." (PMID 36178979, 2022). "In patients with T1D, an episode of two-hour hypoglycemia was followed by an increase in the levels of soluble ICAM-1 (sICAM-1) and IL-6." (PMID 34360550, 2021). "The inflammatory response in severe hypoglycemia was restricted to HSPA1A (HSP70), which correlated with IL-6 in the control subjects only." (PMID 34831332, 2021). "It is well known that hypoglycemia-induced release of proinflammatory factors, including TNF-α, IL-1β, and IL-6, plays a critical role in BBB damage." (PMID 29793504, 2018). "It was also reported that certain cytokines such as IFN-γ, IL-6, or TNF-α was responsible for the induced hypoglycemia in normal strains of mice." (PMID 24741590, 2014). "The Zip14 KO mice exhibited decreased circulating IL-6 with increased hepatic SOCS-3 following LPS, suggesting SOCS-3 inhibited insulin signaling which produced the hypoglycemia in this genotype." (PMID 23110240, 2012). "The finding that IL-6 was highest in participants with poorly regulated T1D may therefore reflect not only greater TAR but also increased glycemic instability and hypoglycemia burden, both of which are typically more pronounced in this group." (PMID 41010714, 2025). "INI also reduced early postoperative interleukin-6 (IL-6) levels without affecting the incidence of hypoglycemia or pain scores." (PMID 41312480, 2025). "Multiple factors are involved in the development of hypoglycemia-induced brain injury, such as oxidative stress, heightened production of reactive oxygen species, elevated levels of inflammatory factors like TNF-α and IL-6, and the activation of MMP9." (PMID 39004753, 2024). "Hypoglycemia leads to a physiological response not only of counter-regulatory hormones such as glucagon, cortisol, catecholamines and growth hormone, but also of cytokines such as TNF-α, IL-6, IL-8 and VEGF-A." (PMID 37400734, 2023).
Hypoglycemia (continued). "Along with the drive of the sympathoadrenal activation, several inflammatory markers including C-Reactive Protein (CRP), Interleukin 6 (IL-6), Interleukin 8 (IL-8), Tumor Necrosis Factor α (TNF-α), and endothelin-1, have been shown to be increased during hypoglycemia." (PMID 34572493, 2021). "Pro-inflammatory interleukin-6 increased at 4-h post-hypoglycemia in controls and T2D (p < 0.05 and p < 0.003, respectively) and correlated with HSPA1A; anti-inflammatory IL-10 decreased 2-h post-hypoglycemia in T2D only." (PMID 34426634, 2021). "Insulin-induced hypoglycemia in nondiabetic male subjects was associated with increased proinflammatory cytokines (TNF-α, IL-1β, IL-6, and IL-8), indicators of lipid peroxidation and ROS production." (PMID 33123598, 2020). "To determine whether the effect of AQP4 deletion on BBB disruption after hypoglycemia is involved in the immunomodulatory influence of AQP4 deletion, we examined TNF-α, IL-1β, and IL-6 mRNA expression in the brains of mice." (PMID 29793504, 2018). "In contrast to hypoglycemia, 24 h hyperglycemic exposure did not alter total cellular Nrf-2 expression total or the endothelial release of IL6, at either 3 or 24 h exposure, as compared to controls." (PMID 24708805, 2014). "Similarly to previous studies, after 2 h of hypoglycemia FMD significantly decreased, while sICAM-1, 8-iso-PGF2a, nitrotyrosine and IL-6 significantly increased, compared to basal values." (PMID 23806096, 2013). "Furthermore Gel showed severe hypoglycemia, acidosis and significantly increased ALT and IL-6 with a lethality of 29%." (PMID 23245375, 2012).
joint disease (41 papers, 2009 to 2025). "Baseline CRP, SAA, and IL-6 levels were positively associated with baseline joint disease severity as measured by the DAS28-CRP (p ≤ 0.0001 for each biomarker)." (PMID 37587493, 2023). "Based on the analysis, we further found one OA case with high IL-6 and low IL-11 levels (10731 ng/ml IL-6 vs. 1255 ng/ml IL-11) in the synovial fluid of the right knee associated with recurrent joint effusion and progressive OA joint damage." (PMID 30197757, 2018). "Joint disorders that are inflammatory and degenerative are associated with IL-6 and sIL-6R." (PMID 39204123, 2024). "Moreover, markers associated with low inflammation levels, such as TNF-α, IL-6, and IL-1β, are under extensive investigation and are proposed as discriminators between OA and other joint disorders characterized by a severe inflammatory component." (PMID 38785519, 2024). "Additionally, multiple AI’s have increased levels of certain inflammatory markers such as TNF-a, IL-6, and IL-17 that have been shown to contribute to arthropathy and are also linked to increased levels of gut dysbiosis." (PMID 37371676, 2023). "In fact, worsening of joint disease was associated with a marked increase of local proinflammatory cytokines (IL-6, IL-1β, and TNF-α) responsible for articular damage, together with sustained levels of monokines and a consequent enhanced inflammatory cell influx." (PMID 19606256, 2009). "Serum IL-6 levels exhibited a downward trend, joint effusion was significantly reduced compared to previous instances." (PMID 40673198, 2025). "IL-6 has an important role in inflammation and tissue destruction in joint diseases such as RA, and its concentration is elevated in the synovial fluids of arthritic patients." (PMID 26839464, 2015). "IL-6 receptor subunit gp130 transgenic mice that have excess spontaneous IL-6 signaling have been reported to develop a joint disease that is similar to RA which is triggered by lymphocyte activation and accompanied by autoantibody formation." (PMID 19368720, 2009). "IL-6 is a key pro-inflammatory cytokine in numerous joint diseases." (PMID 33796579, 2021). "However the association between a number of measures of inflammation including joint disease activity and IL6 levels remained significant on adjustment for traditional risk factors." (PMID 28400572, 2017). "IL-6 is required for the development of collagen-induced arthritis (CIA), and blocking IL-6 receptors improved joint disease in CIA mice." (PMID 38711497, 2024). "The elevated levels of IL-1β, IL-6, and TNF-α, as well as of MMPs, found in the SF of both OA and RA patients confirmed their important role in the pathogenesis of these joint diseases." (PMID 35955467, 2022). "s-JIA/AOSD patients with an IL-6–dominant pattern (s-JIA:IL-18/IL-6 <1000, AOSD IL-18/IL-6 <5000) had more severe joint disease, whereas those with an IL-18–dominant pattern (s-JIA:IL-18/IL-6 >1000) had a more severe systemic disease and developed MAS." (PMID 36211331, 2022). "The production of inflammatory mediators like IL-6 and TNF-α show a critical role in the advancement of joint disorder, bone distortion, pain, and tenderness." (PMID 33919084, 2021). "In murine models of joint disease TNC drives the synthesis of pro-inflammatory cytokines and chemokines such as TNF, IL6 and IL8, which in turn mediate the synthesis of tissue-destructive enzymes." (PMID 23193984, 2012). "Besides, we also found that TRAP was positively correlated with IL-1 β, IL-6, TNF-α, and type II collagen in joint effusion." (PMID 33706812, 2021). "Studies involving specific IL-6 inhibitors have suggested that IL-6 may not be the primary driver of joint disease in PsA." (PMID 40343299, 2025).